AHR (aryl hydrocarbon receptor)
Diseases named in the same sentence as AHR in open-access papers (continued):
Sharing a sentence is not in itself a finding about the gene and the disease.
tumor (continued). "Complementing these findings, our prior work revealed that I3A promotes tumor immunogenicity via downregulation of AHR and c-Myc signaling pathways." (PMID 41354345, 2025). "The aryl hydrocarbon receptor (AhR) plays a pivotal role in modulating immune responses and tumor progression, and recent studies have positioned AhR as a compelling target for immunotherapy." (PMID 41155994, 2025). "Tumor‐reproducing cells drive PD‐1 upregulation in CD8+ T cells via the transcellular Kyn‐AhR pathway, amplifying both immunosuppressive and protumor effects." (PMID 41332472, 2025). "Lactobacillus gallinarium releases indole-3-carboxylic acid (ICA), which competes with kynurenine to bind AhR and inhibit tumor-infiltrating Tregs, resulting in increased IFN-γ+ CD8+ T cells in tumors and increased response to anti–PD-1 treatment." (PMID 39895632, 2025). "For instance, the use of AHR antagonists exhibits anti-tumor activity for several tumor types and in combination with immunotherapy." (PMID 40077746, 2025). "The data suggest that the AhR is a key mediator of tumor immunosuppression through regulation of IFN-induced INCR1 and JAK/STAT signaling and, thereby, expression of immune checkpoints." (PMID 40449595, 2025). "Dysregulation of key signaling pathways such as NF-κB, MAPK, PI3K/Akt/mTOR, and Kynurenine/AhR highlights how microbiota-driven mechanisms promote tumor growth and facilitate immune evasion." (PMID 40075568, 2025). "More importantly, AhR inhibition abolished the increased cytotoxicity of trained macrophages against B16‐F10 tumor cells, establishing AhR as a key driver of reuterin‐induced trained immunity." (PMID 40587842, 2025). "The involvement of the AhR in these alternative signaling pathways and the mechanisms through which it affects tumor-mediated immunosuppression remain to be determined." (PMID 40449595, 2025). "Since several SNPs were associated with AHR mRNA expression, the SCAN-B cohort was used for investigation of the differential impact of tumour AHR mRNA expression according to ER status." (PMID 40646277, 2025). "Elevated kynurenine levels suppress antitumor immune responses by activating regulatory T cells and aryl hydrocarbon receptor signaling, fostering an immunosuppressive tumor microenvironment." (PMID 40239839, 2025). "Only patients with ER+ tumours were included in the interaction analyses between AHR genotypes and adjuvant endocrine treatments." (PMID 40646277, 2025). "In KPIC orthotopic PC mice, inhibition of the IDO1/TDO2-Kyn-AhR pathway resulted in delayed tumor growth, suppressed tumor metastasis, and enhanced tumor cell apoptosis." (PMID 40136551, 2025). "Upon AhR activation, kynurenine can inhibit effector T cell function and promote Treg differentiation, thereby facilitating immune evasion and tumor progression." (PMID 40771692, 2025). "Instead, we observed consistent co-expression between IDO2 and AhR, particularly in tumour-dense regions, suggesting a role in sustaining immunosuppression." (PMID 40471422, 2025). "Collectively, tryptophan-derived metabolites exert pleiotropic and often contradictory effects: they can potentiate CD8+ T-cell responses and improve immunotherapy efficacy, yet also fuel tumor progression via myeloid-AhR activation or ferroptosis suppression." (PMID 41339918, 2025). "Kynurenine also acts as an endogenous ligand for the aryl hydrocarbon receptor (AhR), promoting tumor immune evasion and progression." (PMID 40843669, 2025). "In gastric cancer, glutathione peroxidase‐2 supports tumor progression through the KYNU‐Kyn‐AhR signaling pathway, while glutathione peroxidase‐2 knockdown suppresses tumor growth and metastasis." (PMID 41332472, 2025). "AhR has both pro- and anti-tumour regulatory effects depending on the context and immune cell subset." (PMID 40646277, 2025). "Our results add to the emerging evidence for a dual role of physiological AhR activation in anti-tumor immune responses." (PMID 41331250, 2025).
tumor (continued). "In melanoma, gut-derived Lactobacillus reuteri migrates to the tumor and catabolizes dietary Trp into indole-3-aldehyde (I3A), which activates the AhR–cAMP CREB–Blimp-1 signaling cascade in CD8+ T cells." (PMID 41516132, 2025). "In PDAC, strong changes in AHR activity in both immune and tumor cells contribute to an immunosuppressive environment." (PMID 41357201, 2025). "IDO1 and TDO2 are the first rate-limiting metalloenzymes that are responsible for the degradation from TRP to kynurenine, which is closely correlated to the failure of anticancer immunotherapies and tumor progression through the activation of AhR." (PMID 41255573, 2025). "Our aim was to explore the correlation between key KP markers; IDO1, IDO2, TDO2, its primary effector target aryl hydrocarbon receptor (AhR) and a comprehensive set of clinical- and tumour characteristics." (PMID 40471422, 2025). "We propose that the balance between these opposing activities–immunostimulation versus cytoprotection–likely depends on host immune status, microbiota composition, specific tumor microenvironment interactions, and relative activation of AHR pathways." (PMID 41354345, 2025). "The crosstalk between AhR activation and tryptophan (Trp) metabolism, especially via the kynurenine (Kyn) pathway, constitutes a pivotal regulatory axis in tumour immune evasion." (PMID 41275427, 2025). "The aryl hydrocarbon receptor (AhR) ligand, a tumour suppressor gene when restored functionally, can act as an anti-cancer agent." (PMID 40806481, 2025). "Consistent with this concept, recent work has demonstrated metabolism-directed strategies to overcome EGFR-TKI resistance, including inhibition of BCAT1/BCAA metabolism and disruption of kynurenine–AHR signaling in the tumor microenvironment." (PMID 41142757, 2025). "The aryl hydrocarbon receptor (AHR) promotes tumor growth, metastasis, genomic instability and chemoresistance, augments immune evasion and has been associated with poorer patient outcome." (PMID 40642792, 2025). "This study offers novel insights into the complex regulation of TOX by AHR, highlighting that AHR functions as a tumor suppressor by repressing TOX transcription." (PMID 40303305, 2025). "Tumour-derived kynurenine activates the aryl hydrocarbon receptor (AHR) pathway, which in turn suppresses glycolysis." (PMID 41429765, 2025). "Indole and its derivatives, as metabolites of tryptophan, play different roles in various environments, and the role of AhR activation in tumor progression is ligand‐specific." (PMID 40103267, 2025). "We extracted proteins and RNA from these xenograft tumours and found that LM10 significantly reduced the protein levels of AhR in castration-recurrent tumours." (PMID 40759641, 2025). "For example, in our hands, AhR deletion in oral squamous carcinoma cells renders mice 100% immune to further challenge with wild-type tumor cells." (PMID 40449595, 2025). "Indole-3-carboxaldehyde, a metabolite derivative from tryptophan catabolism, modulates tumor progression and immune responses through activation of the aryl hydrocarbon receptor (AHR)." (PMID 40710368, 2025). "Indoleamine 2,3-dioxygenase (IDO) activity was stimulated by LPS in resident antigen-presenting cells and tumor cells, leading to the increased production of Kyn from tryptophan, which activated AHR and subsequently led to increased immune tolerance." (PMID 40765830, 2025). "In AHR-high tumours, oestrogen responses, myogenesis and hypoxia hallmarks were enriched only in ER+ tumours." (PMID 40646277, 2025). "Our aim is to investigate the KP with a broadened scope, exploring the IDO1, IDO2, TDO2 and AhR interplay with both clinical as well as tumour characteristics." (PMID 40471422, 2025). "The data support targeting the AHR pathway as a dual tumor intrinsic and immune targeting therapeutic strategy for AML, particularly in combination with NK cellular therapy." (PMID 41445756, 2025).
tumor (continued). "The aryl hydrocarbon receptor is a ligand-sensitive transcription factor that plays a key role in the regulation of immune function and tumor development." (PMID 41357201, 2025). "In gastric cancer, GPx2 knockdown‐induced ROS accumulation promotes KYNU expression, which subsequently degrades Kyn, thereby inhibiting AhR‐mediated tumor progression and EMT." (PMID 40103267, 2025). "In conclusion, we identify first insights into the complex nature of circadian driven regulation of AHR function in human cells, in particular in human breast epithelia non-tumor cells." (PMID 40936027, 2025). "The transcription factor aryl hydrocarbon receptor (AHR) plays important roles in the intestine, limiting tumour growth and promoting the normal epithelial lining." (PMID 40212817, 2025). "Lactobacillus species convert dietary tryptophan into indoles, which activate the aryl hydrocarbon receptor (AhR) in the tumor microenvironment." (PMID 40927726, 2025). "Recent research has highlighted AHR's complex dual role in carcinogenesis, where it can act as either a tumor promoter or suppressor depending on cellular context." (PMID 40303305, 2025). "Oral administration of 3‐IAA increased the expression of 4‐hydroxynonenal (4‐HNE) in tumor tissues, an effect that was reversed upon AhR knockdown." (PMID 40557796, 2025). "Previous studies suggest that AHR exhibits tumor-suppressive effects in As3+-induced carcinogenesis." (PMID 40303305, 2025). "TAMs exhibit high aryl hydrocarbon receptor (AhR) activity, and studies have shown that tryptophan-derived microbial metabolites can activate AhR in TAMs, thereby suppressing anti-tumor immunity." (PMID 40131539, 2025). "The authors here identify that diet containing indole-3-carbinol improves anti-tumor immunity of anti-PD1 therapy via AhR on CD8 T cells." (PMID 41331250, 2025). "This metabolic reprogramming, focusing on the IDO–kynurenine–AHR axis, offers a plausible mechanism for tumor growth and immune evasion, linking these “benign” neoplasms to the established hallmarks of malignancy." (PMID 41470122, 2025). "When comparing AHR expression levels in normal tissue, primary tumors, and metastatic sites, we observed the lowest AHR expression in metastases, followed by tumor tissues." (PMID 40303305, 2025). "Hallmarks found only in ER- AHR-high vs. AHR-low tumours were interferon alpha (IFN-α) response, angiogenesis, peroxisome and fatty acid metabolism." (PMID 40646277, 2025). "We then sought to decipher what gene programs are controlled by AhR during reinvigoration of tumor-infiltrating T cells mediated by anti-PD1." (PMID 41331250, 2025). "In AHR-high ER- tumours, nine genes were upregulated and three genes were downregulated compared with AHR-low tumours." (PMID 40646277, 2025). "Together, these findings suggest that TOX functions as an oncogenic factor and that AHR's tumor-suppressive role is, at least in part, mediated by repressing TOX expression." (PMID 40303305, 2025). "Mechanistically, HMP1G NPs downregulated tumor cell‐derived IDO1 via the aryl hydrocarbon receptor/signal transducer and activator of transcription 3/interleukin signaling axis to improve kynurenine/tryptophan metabolism and immunosuppression." (PMID 39661740, 2025). "Recent mechanistic studies further confirm the role of AHR in macrophage plasticity within the tumor microenvironment." (PMID 41357201, 2025). "Growing evidence suggests that AhR activation promotes tumor cell migration and contributes to drug resistance in breast and pancreatic cancer and GBM." (PMID 40149846, 2025). "The aryl hydrocarbon receptor (AHR) plays important roles in intestinal homeostasis, limiting tumour growth and promoting differentiation in the intestinal epithelium." (PMID 40212817, 2025). "Deletion of AhR in TAMs or pharmacologic inhibition of AhR reduced PDAC tumor growth, improved efficacy of immune checkpoint blockade, and increased intratumoral frequencies of IFN‐γ+ CD8+ T cells." (PMID 40223597, 2025).
tumor (continued). "The AhR- and HCAR3-dependent pathways have been implicated in the microbiota-mediated immunomodulation of the tumor microenvironment in gastric cancer." (PMID 40650047, 2025). "To conclude, this Kyn–AhR axis serves as a critical regulator of STING‐mediated tumour‐suppressive effects." (PMID 41275427, 2025). "The immunosuppressive role of IDO1 within the Kyn-AhR axis in GBM tumour environment has been extensively studied in the past decade." (PMID 40471422, 2025). "The connection between tryptophan metabolism and tumor progression was highlighted when the removal of tryptophan from the diet reduced AhR activity in TAMs." (PMID 40927726, 2025). "DGE analyses were performed tumours with high (T3) versus low (T1) AHR expression stratified by ER status." (PMID 40646277, 2025). "Particularly in the treatment resistance phase, the AhR signaling pathway can be co-opted by tumor cells to foster disease progression." (PMID 41585883, 2025). "In turn, they regulate the tumor cell cycle, promotes antioxidant responses, and influences gene expression through aromatic hydrocarbon receptor (AHR)-mediated signaling, which ultimately promotes the survival and proliferation of tumor cells." (PMID 40356913, 2025). "Resveratrol abrogated deleterious AhR, sustained activation in these cells, and reduced the number of BRAFi-resistant cells, thus delaying tumor growth." (PMID 39339278, 2024). "AhR expression is important in monocyte-derived type 1 DC differentiation, which plays an important role in the anti-tumor response." (PMID 38339226, 2024). "Given that STING activation is essential for proper PARPi-mediated anti-tumor efficacy, it would be interesting to investigate if microbiome-dependent AhR activity contributes to the disparities among patient responses to PARPi treatment." (PMID 38459088, 2024). "For example, AhR has been shown to have tumor suppressor activity in various cancer types including intestinal, prostate, lung, and liver (reviewed in32)." (PMID 38459088, 2024). "Similar to those in HNSCC, the AhR expression levels in specific immune cell types (macrophages, T cells, and Tregs) in the tumor nest were positively correlated with the stromal ones." (PMID 38680496, 2024). "The AHR is activated in TAMs by microbial metabolites generated from tryptophan, leading to the suppression of anti-tumor immunity." (PMID 39351241, 2024). "The role of IL22 and, therefore, AhR-dependent T helper cell differentiation in cancer progression, is context dependent, with both pro-tumor and anti-tumor roles described." (PMID 38339226, 2024). "CYP1A1 is a major enzyme that plays a role in carcinogenesis and tumor progression by inducing AhR by binding environmental pollutants such as B[a]P and inhaling chemicals that mitigate their biological and toxic effects." (PMID 38276538, 2024). "In the context of cancer, AhR has been found to have complex roles, acting as a tumor suppressor in some cases, while promoting tumor growth and invasion in others, depending on the cellular context and the types of ligands activating it." (PMID 39763643, 2024). "This is because AHR exhibits both pro- and anti-tumorigenic effects which are ligand-, cell- and tumor type-dependent." (PMID 39450255, 2024). "Tryptophan-derived metabolites can aid immune escape from tumors by activating the AhR of TAM, and expression of the AhR in TAM has a profound impact on tumor growth and TME." (PMID 38434684, 2024). "AHR activation can promote tumor growth by inducing the expression of genes involved in cell proliferation and survival, angiogenesis, and inflammation." (PMID 38868519, 2024). "Aryl hydrocarbon receptor (AHR) is a ligand-activated transcription factor that, when chronically activated, has a strong role in supporting tumour invasion, migration, and metastasis including in HNSCC." (PMID 38474047, 2024). "There are significantly conflicting reports of AhR functioning as either a pro-tumorigenic or a tumor-suppressive factor in cancer." (PMID 38791215, 2024).
tumor (continued). "AHR also functions as a sensor of microbiome-derived metabolites, modulating immune function within the tumor microenvironment." (PMID 38612627, 2024). "Conversely, AhR signaling has also been shown to enhance anti-tumor immune responses by promoting Th17 cell differentiation, highlighting its complex role." (PMID 39835132, 2024). "Another significant study provided evidence that AhR activation with specific ligands increases AR transcriptional activity, leading to enhanced tumor cell proliferation." (PMID 39184676, 2024). "Although some studies provide evidence that activation of AhR pathway promotes carcinogenesis, others suggest an opposite function of AhR as a tumor suppressor." (PMID 38518996, 2024). "With the contrasting roles of AhR activation on immune cell polarization, understanding the impact of AhR activation on the tumor immune microenvironment is necessary to guide therapies targeting the AhR." (PMID 38339226, 2024). "The AhR expression levels in each immune cell type (macrophages, T cells, and Tregs) within the tumor nest were positively correlated with the stromal AhR expression in the corresponding cell type, consistent with the findings observed in similar cancer types." (PMID 38680496, 2024). "Formate secreted by Fusobacterium nucleatum can set off the AhR pathway, thus promoting CRC tumor invasion, and can serve as a tumor metabolite associated with CRC progression." (PMID 38450163, 2024). "Protein expression predominantly clustered within high-density tumor cell regions, notably with AhR and IDO2 demonstrating markedly elevated levels compared to IDO1 and TDO2." (PMID 38951170, 2024). "Eucalyptol acted as an AhR inhibitor and also delayed tumor incidence and the tumor numbers in the UVB-induced SKH-1 mice, while inhibiting COX-2 expression when applied topically." (PMID 38674007, 2024). "In this review, we comprehensively summarize the increasingly controversial role of AhR as a tumor regulator and the mechanisms by which it alters tumor progression based on the cancer cell type." (PMID 38807762, 2024). "This manipulation of TAMs appears dependent on the induction of arylhydrocarbon receptor (AHR) expression through IDO induction within tumor cells." (PMID 38185636, 2024). "The catabolic product of tryptophan, KYN, can induce cancer cell invasion and immune suppression of the tumor microenvironment by binding to AhR." (PMID 39408347, 2024). "Increasing evidence shows that the aryl hydrocarbon receptor (AHR) plays a crucial role in neoplastic disease progression, establishing it as a potential drug target." (PMID 39204085, 2024). "Understanding the impact of AhR activation on the tumor immune microenvironment is critical to guide cancer therapies targeting the receptor." (PMID 38339226, 2024). "This Kyn-AhR pathway has been validated in both tumor-bearing mice and patients with cancer, and blocking this pathway enhances the effectiveness of adoptive T cell therapy against tumors." (PMID 38786085, 2024). "In liver cancer, AhR activation prevents tumor cells from entering the G0/G1 phase, which reduces DNA replication and prevents cell proliferation." (PMID 38434684, 2024). "AHR influences the tumor microenvironment by modulating the activity of immune cells, including T cells and macrophages, which are essential for anti-tumor immunity." (PMID 39600743, 2024). "In summary, AhR is an important target for enhancing tumor adaptation, tumor immune evasion, and monitoring changes in the TME." (PMID 38434684, 2024). "Given the importance of AhR in pathologic immune cell polarization, its role in carcinogenesis, and impact on tumor immune evasion, targeting AhR offers an exciting opportunity for cancer therapy." (PMID 38339226, 2024). "Aryl hydrocarbon receptor (AhR) has been known to regulate the activity of immune cells and tumor development through EMT modulation by transforming epithelial cells towards malignancy form." (PMID 38361941, 2024).